NLRP3 (NLR family pyrin domain containing 3)
Diseases named in the same sentence as NLRP3 in open-access papers (continued):
Sharing a sentence is not in itself a finding about the gene and the disease.
atherosclerosis (continued). "The development of atherosclerotic lesions was observed to decrease in LDL-R deficient mice fed a high fat diet when transplanted with bone marrow deficient in NLRP3, ASC, IL-1β, Il-18 or IL-1α, highlighting the importance of the inflammatory pathway in the development of atherosclerosis." (PMID 36459456, 2022). "Although several types of inflammasomes have been described so far, including NLRP1, NLRP2, NLRP3, NLRC4 and AIM2, the most characterized and studied has been NLRP3, due to its clinical importance in a wide range of pathologies, such as atherosclerosis, diabetes or IBD." (PMID 35327334, 2022). "As an inflammasome of NLRP3, IL-18 can accelerate atherosclerosis in mice." (PMID 35785176, 2022). "Trx-1 could inhibit the NLRP3 inflammasome leading to an attenuation of atherosclerosis and was able to exert protective effects." (PMID 35496300, 2022). "This process possibly involves the activation of thioredoxin-interactive protein linked to NLRP3 signaling, via reactive oxygen species (ROS-TXNIP-NLRP3) and the tight-junctions disruption and alteration of endothelial cells permeability leading atherosclerosis." (PMID 36317116, 2022). "In macrophages, activation of NLRP3 inflammatory vesicles can stimulate the formation of cholesterol crystals, which are necessary for the development of atherosclerosis; activation is an important mechanism driving the development of atherosclerotic inflammation." (PMID 36589841, 2022). "Similarly, our investigation of diabetic atherosclerosis of ApoE−/− mice revealed the enhanced expression level of NLRP3-ASC and GSDMD in the atherosclerotic plaques of endothelial cells with aortic sinus." (PMID 36425580, 2022). "NLRP3‐dependent inflammation is suggested to drive neuroinflammation in neurodegenerative conditions including Alzheimer's and Parkinson's disease in addition to peripheral diseases such as atherosclerosis, type‐2 diabetes, and others." (PMID 35353387, 2022). "Notably, intracellular protein NACHT, LRR, and PYD domain-containing protein 3 (NLRP3) form the NLRP3 inflammasome, which mediates the effects of IL-1β related to atherosclerosis." (PMID 35563294, 2022). "More recently, knockdown of NLRP3 also exhibited remarkable effect on lowering blood pressure, improving vascular remodeling and insulin resistance, and ameliorating or delaying the atherosclerosis via regulating metabolism, relieving oxidative stress and reducing release of inflammatory cytokines." (PMID 36703963, 2022). "The present study has revealed that miR-99a-5p might inhibit NLRP3 inflammasome activation and promote macrophage autophagy by targeting mTOR, therefore, alleviating atherosclerosis." (PMID 35968506, 2022). "Mice treated with NLRP3 inhibitors or NLRP3 genetic deletions sufferless atherosclerosis." (PMID 39077721, 2022). "An increase in NLRP3 inflammasome formation in endothelial cells is also activated by increased integrin α5 in lipid rafts due to the presence of oxidised low-density lipoprotein and oscillatory shear stress, contributing to the development of atherosclerosis." (PMID 35528818, 2022). "Our studies reveal that SORBS2 silencing inhibited activation of the NLRP3/ caspase-1/ IL-1β pathway, ultimately blocking the inflammation process in AS, and thus potentially providing protection against hypercholesterolemia and atherosclerosis." (PMID 35590369, 2022). "However, ApoE−/− mouse models of atherosclerosis have generated some controversy around the role of the NLRP3 inflammasome." (PMID 36459456, 2022).
atherosclerosis (continued). "NLRP3 inflammasome and the downstream pro-inflammatory cytokines IL-1β and IL-18 are attractive pharmaceutical candidates for therapeutic intervention of atherosclerosis, and selectively neutralizing these cytokines has been shown to be available in the context." (PMID 35459215, 2022). "We next briefly introduce the role of NLRP3 in DM and atherosclerosis." (PMID 35844498, 2022). "We next discuss the specific mechanism of action of NLRP3 in DM-promoting atherosclerosis." (PMID 35844498, 2022). "Moreover, it was shown that the activation of the NLRP3 inflammasome in atherosclerosis via the SIRT3-SOD2-mtROS signaling pathway promotes inflammation in HUVECs." (PMID 35719709, 2022). "Moreover, accumulating evidence has shown that NLRP3 activation products IL-1β and IL-18 both play an important role in the occurrence of atherosclerosis." (PMID 35844498, 2022). "The NLRP3 inflammasome plays an important role in the molecular etiology of atherosclerosis." (PMID 36589841, 2022). "NLRP3 plays an important role in both diabetes and atherosclerosis." (PMID 35844498, 2022). "Interestingly, colchicine, an alkaloid derived from autumn crocus (Colchicum autumnale), has already been shown to inhibit NLRP3 inflammasome oligomerization in patients with atherosclerosis." (PMID 36012243, 2022). "Mechanistically, this study further elucidated the crosstalk between lipids and inflammation remaining in macrophages, in which the NLRP3 inflammasome and its downstream IL-1β act as executors to initiate the inflammatory response that ultimately leads to atherosclerosis." (PMID 35864109, 2022). "Therefore, the inhibition by ox-LDL-induced NLRP3 activation and inflammatory response in macrophages are key to intervening in the formation of atherosclerosis plaque." (PMID 36557935, 2022). "Therefore, the NLRP3 inflammasome has attracted interest as a targetin atherosclerosis due to its ability to generate both active forms ofIL-1β and IL-18." (PMID 39077721, 2022). "For instance, NLRP3 has been found to be negatively modulated by CS exposure in human THP1 cells and in mice, whereas other studies indicate NLRP3 activation upon CS insult in bronchial epithelial cells and other pathologies as atherosclerosis, vascular and bladder dysfunctions, or brain injury." (PMID 35428946, 2022). "By inducing autophagy, atorvastatin reduces the vulnerability of atherosclerosis plaques in mice, inhibits the inflammatory response, and activates the NLRP3 inflammasome, as well as inhibiting foam cell formation and inflammatory cytokine secretion in macrophages stimulated with ox-LDL." (PMID 36671400, 2022). "NLRP3 inflammasomes are involved in cigarette-smoke-induced atherosclerosis." (PMID 35563387, 2022). "The mechanismsby which NLRP3 inflammasome inhibits atherosclerosis also requires furtherstudies." (PMID 39077721, 2022). "In sharp contrast, a deletion of the NLRP3 inflammasome component in Apoprotein E–deficient (ApoE−/−) mice had no significant impact on atherosclerosis." (PMID 35641492, 2022). "NLRP3 inflammasome favors vascular ECs injury, the infiltration of monocytes/macrophages, and the formation of foam cells, thus, represent an important proinflammatory contributor to atherosclerosis development and progression." (PMID 36362423, 2022). "Accordingly, ablation of the NLRP3 inflammasome pathway decreases atherosclerosis progression." (PMID 33716981, 2021). "To summarize, ox-LDL and CCs in macrophages of patients with CVD activate the NLRP3 inflammasome to promote the development of atherosclerosis, which, in turn, induces a systemic inflammatory state that provides a favorable scenario for infection with SARS‐CoV‐2." (PMID 34522180, 2021).
atherosclerosis (continued). "Here, we aim to identify the essential role of lipid raft in mediating nicotine-triggered inflammatory and nicotine-accelerated atherosclerosis, and to figure out the specific receptor of nicotine-induced Nod-like receptor protein 3 (NLRP3) inflammasome activation in macrophage." (PMID 34490270, 2021). "This study also revealed the importance of NLRP3 activation in the development of atherosclerosis." (PMID 32378144, 2021). "However, further studies are necessary to investigate the causal relationship between exercise training and ER stress-induced TXNIP/NLRP3 inflammasome signaling in coronary arterioles in atherosclerosis." (PMID 34326395, 2021). "As several experimental and clinical reports have demonstrated that IL-1β is a proatherogenic cytokine, NLRP3 inflammasome activation could contribute to the progression of atherosclerosis." (PMID 33807807, 2021). "One of NLRP3 inflammasome has been shown to be involved in the development of a variety of inflammatory-related diseases, such as type 2 diabetes, gout, atherosclerosis, neurodegenerative diseases, cancer, and inflammatory bowel disease." (PMID 34526897, 2021). "Nicotine induces the production of various inflammatory factors, such as interleukin-1β (IL-1β), nuclear factor-κβ, and necrosis factor-α, and NLRP3 inflammasome-mediated pyroptosis was recently considered to be an important pathogenicmechanism on atherosclerosis." (PMID 34490270, 2021). "Consequently, NLRP3 inflammasome activation is deeply involved in the vascular inflammatory response driving development and progression of atherosclerosis." (PMID 34070931, 2021). "Indeed, the ablation or inhibition of the NLRP3 inflammasome pathway decreases atherosclerosis progression, thus emphasizing the critical role of NLRP3 in atherosclerosis initiation." (PMID 34575881, 2021). "Our in vivo study showed that NLRP3 inflammasome-mediated endothelial cell pyroptosis may be involved in atherosclerosis progression." (PMID 33839695, 2021). "NLRP3 can sense diverse stimuli including pathogen components, environment irritants, and host danger effectors, so its aberrant activation leads to many inflammatory diseases, such as sepsis, gout, type 2 diabetes, atherosclerosis, and Alzheimer’s disease." (PMID 35095532, 2021). "Chronic NLRP3 inflammasome activity worsens the course of atherosclerosis." (PMID 34070553, 2021). "Moreover, NLRP3 blockade was shown to alleviate the inflammatory injury induced by cholesterol crystals in atherosclerosis." (PMID 34512861, 2021). "Similarly, atherosclerosis is characterised by NLRP3 activation following deposition of cholesterol crystals in the walls of blood vessels." (PMID 33970350, 2021). "NLRP3 inflammasome is key to a variety of disease processes: from the first identified familial recurrent auto-inflammatory responses to type 2 diabetes, Alzheimer’s disease, and atherosclerosis." (PMID 34912814, 2021). "The lncRNA MEG3/miR‐223/NLRP3 axis in atherosclerosis promotes endothelial cell pyroptosis." (PMID 33270361, 2021). "However, the aberrant activation of the NLRP3 inflammasome leads to pathological inflammatory disorders, including AD, PD, atherosclerosis, arthritis, and cancer." (PMID 34439462, 2021). "The NLRP3 inflammasome is also involved in the formation of atherosclerosis." (PMID 34502177, 2021). "However, the underlying mechanism by which the cholesterol homeostatic regulator SCAP-SREBP2 mediates NLRP3 in?ammasome activation in vascular inflammation and atherosclerosis is unclear." (PMID 34094640, 2021). "Although Eri clinical application needs optimization of treatment options and integrated safety assessment, Eri may serves as a potential treatment for NLRP3-driven diseases, including IV infection, T2D, atherosclerosis and gout." (PMID 34745110, 2021).
atherosclerosis (continued). "Furthermore, the current (pre)clinical therapeutic approaches targeting the NLRP3 inflammasome and its downstream signaling cascade in atherosclerosis, CAD, and myocardial I/R injury are discussed." (PMID 32648087, 2021). "Accordingly, blocking the activation of NLRP3 inflammasome may be a promising treatment strategy to blunt the progression of atherosclerosis." (PMID 33783966, 2021). "Thus, this would seem to suggest that P2X7R is involved in the progression of atherosclerosis by promoting the activation of the NLRP3 inflammasome." (PMID 32378144, 2021). "Aberrant activation of the nucleotide-binding domain and leucine-rich repeat related (NLR) family, pyrin domain containing 3 (NLRP3) inflammasome drives the development of many complex inflammatory diseases, such as obesity, Alzheimer's disease, and atherosclerosis." (PMID 34646372, 2021). "Excessive intracellular accumulation of cholesterol in macrophages due to a decrease in the transport function of ABCA1 contributes to the initialization of NLRP3 (NLR family pyrin domain containing 3) inflammation, which makes a significant contribution to the progression of atherosclerosis." (PMID 34201488, 2021). "In addition, Metformin was shown to inhibit NLRP3 inflammasome activation, and suppressed atherosclerosis in ApoE−/− mice, at least partially through activation of AMPK and regulation of Trx-1/TxNIP." (PMID 35008500, 2021). "In conclusion, SGLT2i attenuates the activation of NLRP3 inflammasome, which might help explain its inhibitory effect on atherosclerosis." (PMID 33754074, 2021). "In addition, other atherosclerosis-relevant stimuli, such as disturbed blood flow, can augment NLRP3 inflammasome activation." (PMID 35008500, 2021). "The NLRP3 inflammasome is regarded as an important initiator in diverse human diseases, including type 2 diabetes (T2D), gout, obesity, atherosclerosis, neurodegenerative diseases, cancer, and inflammatory diseases, and has been suggested as a potential target for the treatment of these diseases." (PMID 34571975, 2021). "Furthermore, we demonstrated that pharmacological interventions targeting the UCP1/MMP/NLRP3 inflammasome–IL-1β axis are promising therapeutic strategies for the treatment of atherosclerosis in small- and large-animal models." (PMID 34878840, 2021). "Furthermore, the current therapeutic approaches targeting the NLRP3 inflammasome and its downstream signaling cascade in atherosclerosis, CAD, and myocardial I/R injury are discussed." (PMID 32648087, 2021). "Given this pivotal role of NLRP3 inflammasome in atherosclerosis, it is important to examine whether a connection exists between smoking/nicotine and inflammasome activation." (PMID 33626512, 2021). "We found that VSMCs (Myh11+) undergoing transdifferentiation to macrophages-like cells in human atherosclerotic plaques co-express cleaved caspase 1 as well as IL-1β, indicating the involvement of NLRP3 inflammasome activation in VSMCs phenotypic switch in human atherosclerosis." (PMID 35008765, 2021). "NLRP3 (NLR family pyrin domain containing 3) represents the most prominent inflammasome sensor and its activation is associated with numerous inflammatory diseases, including Alzheimer’s disease, atherosclerosis, and rheumatoid arthritis." (PMID 34206503, 2021). "SGLT2 inhibitors may improve atherosclerosis and cognitive dysfunction via NLRP3 inflammasome inhibition." (PMID 34885795, 2021). "The most studied inflammatory process in atherosclerosis is related with NLRP3 inflammasome." (PMID 33807807, 2021). "Furthermore, this agent has the ability to reduce atherosclerosis progression by activating autophagy in macrophages and inhibiting the NLRP3 inflammasome activity." (PMID 34831370, 2021). "NOD‐, LRR‐ and pyrin domain‐containing protein 3 (NLRP3) inflammasome activation and the resulting pyroptosis are involved in the initiation and vicious circle of chronic inflammation, thus playing an indispensable role in atherosclerosis." (PMID 33783966, 2021).
atherosclerosis (continued). "All the proposed mechanisms for NLRP3 inflammasome activation, such as oxidative stress, mitochondrial dysfunction, ER stress, and lysosome rupture, have been observed in atherosclerosis." (PMID 33807807, 2021). "A previous study found that cholesterol crystals accumulated in the intima in the early stage of atherosclerosis can activate the inflammatory response of macrophages and smooth muscle cells through NLRP3 inflammasomes, and eventually lead to the formation of unstable plaques." (PMID 33839695, 2021). "The NLRP3 inflammasome has emerged as a potent proinflammatory mediator of the innate immune system and a driver of various inflammatory disorders such as sepsis, inflammatory bowel disease, and atherosclerosis." (PMID 34955683, 2021). "Thus, we uncover a role of YAP in regulation of the NLRP3 inflammasome activation, and provide potential therapeutic target to treat a number of inflammatory disorders, such as atherosclerosis, gout, colitis, and sepsis." (PMID 33976226, 2021). "However, there is new evidence showing that the NLRP3 inflammasome plays a more prominent role in atherosclerosis in female mice than in males." (PMID 33692700, 2021). "This review focuses on the role and regulatory mechanism of the NLRP3 inflammasome in atherosclerosis, and the NLRP3 inflammasome could be considered as a potential therapeutic target for AS." (PMID 32328119, 2020). "The authors demonstrated that TET2 loss of function in macrophages exacerbated NLR Family Pyrin Domain Containing 3 (Nlrp3) mediated Interleukin 1 beta (IL-1b) production which in turn accelerated atherosclerosis in a context of CHIP, thereby demonstrating that CHIP leads to increased inflammation." (PMID 32526214, 2020). "Thus, exploring the inflammatory mechanism of atherosclerosis and manipulating the function of NLRP3 inflammasomes have emerged as new approaches to understanding and treating the disease." (PMID 32003754, 2020). "The NLRP3 inflammasome is a cytosolic protein complex consisting of the NLRP3, apoptosis-associated speck-like protein (ASC), and protease caspase-1, which can cleave pro-IL-1β into mature IL-1β, thus aggravating the inflammatory response in atherosclerosis." (PMID 33505579, 2020). "NLRP3 inflammasome is involved in some of these events during atherosclerosis pathogenesis." (PMID 32508013, 2020). "Fucoidan could inhibit NLRP3 inflammasome activation by enhancing p62/SQSTM1-dependent selective autophagy to alleviate atherosclerosis." (PMID 33505579, 2020). "Inhibition of the NLRP3 inflammasome results in decreased inflammation and reduced atherosclerosis." (PMID 33505579, 2020). "Although the NLRP3 inflammasome has been implicated in the pathology of atherosclerosis, disease manifestation in germ free mice is no different to normally housed mice, suggesting sterile priming and activation of the inflammasome." (PMID 32883606, 2020). "In the last few decades, the importance of NLRP3 inflammasome biology has become more apparent in inflammatory diseases, such as Alzheimer’s disease, stroke, inflammatory bowel diseases, and atherosclerosis." (PMID 32121312, 2020). "Similarly, miR-9 was involved in suppression of inflammatory responses in atherosclerosis, wherein miR-9 inhibited the activation of the NLRP3 inflammasome, and thus attenuated atherosclerosis-related inflammation through the JAK1/STAT signaling pathway." (PMID 32765295, 2020). "Intriguingly, microbial pathogens augment atherosclerosis via NLRP3 inflammasome." (PMID 32508013, 2020). "The centrality of NLRP3 inflammasome in atherosclerosis has also been well ascertained." (PMID 33664731, 2020). "CD36 was also reported to activate NLRP3 inflammasome in response to atmospheric particulate matter exposure, as well as modulating lipid accumulation in macrophage, ultimately contributing to the progression of atherosclerosis." (PMID 33008402, 2020). "NLRP3 inflammasomes are also autophagocytosed in atherosclerosis." (PMID 32003754, 2020).